PRL (prolactin)
Diseases named in the same sentence as PRL in open-access papers (continued):
Sharing a sentence is not in itself a finding about the gene and the disease.
hyperprolactinemia (continued). "Baseline prolactin levels should have been obtained, as they help in the management of patients who develop neuroleptic-induced hyperprolactinemia." (PMID 31417404, 2019). "This study presents the first pilot, randomized, controlled trial of chamomile syrup versus cabergoline in reducing prolactin levels in women with idiopathic hyperprolactinemia." (PMID 32641968, 2019). "Chamomile syrup seems to be effective on serum prolactin reduction in women with idiopathic hyperprolactinemia." (PMID 32641968, 2019). "Serum macroprolactin was measured in 48 cases with idiopathic hyperprolactinemia and detected in 5 (10.4%), with a median PRL level of 127 (63.5-200) ng/mL." (PMID 30396878, 2019). "A number of drugs can alter PRL homeostasis leading to hyperprolactinaemia via different mechanisms." (PMID 31847209, 2019). "In the long term, normalization of serum prolactin levels occurs in about 30% of patients with idiopathic hyperprolactinemia and a microprolactinoma appears in approximately 10% of them." (PMID 32641968, 2019). "A clinicalimplication of these findings is proposing hyperprolactinemia (Prolactin values≥20.08 ng/mL) as a probable prognostic biomarker for infertile women withendometriosis stages III/IV vs. I/II." (PMID 30969738, 2019). "It is usually defined by a sustained prolactin level above the laboratory upper level of normal in conditions other than that where physiologic hyperprolactinemia is expected." (PMID 31417404, 2019). "The differentiation between a PRL-secreting tumour and a NFA or other sellar/parasellar mass causing hyperprolactinaemia through “stalk effect” is very important, as these conditions are managed differently." (PMID 31847209, 2019). "Due to the challenges in investigating hyperprolactinaemia in such scenarios, checking baseline PRL levels prior to initiation of antipsychotic medication is recommended aiming to avoid future unnecessary imaging." (PMID 31847209, 2019). "PRL by turn looks to impact ovarian function and long-term hyperprolactinemia is known to hinder the hypothalamus-pituitary axis and endorse anovulatory cycles." (PMID 32082253, 2019). "Experimentally induced systemic hyperprolactinemia (excess of circulating prolactin [PRL]) in rats and in mice results in drastic prostate hypertrophy exhibiting features of human BPH such as epithelium hyperplasia and increased stromal cellularity." (PMID 30984003, 2019). "Hyperestrogenemia was found in 20 of these patients (50%), whereas mild hyperprolactinemia (prolactin less than twice above the upper referent limit) was found in 10 of them (25%); however, no cause for these alterations had been established." (PMID 31687020, 2019). "The aim of this study was to assess the efficacy of chamomile syrup in reducing serum prolactin in women with idiopathic hyperprolactinemia." (PMID 32641968, 2019). "Recovery criterion of ≤ 60% defined 100 patients as macroprolactinaemic; 29 of them had post-PEG PRL above the upper limit of the post-PEG reference interval (true hyperprolactinaemia)." (PMID 31223260, 2019). "Though less likely to elevate prolactin levels than other antipsychotics (e.g., haloperidol and risperidone) hyperprolactinemia prevalence rates of up to 29% have been reported in association with its use." (PMID 29515515, 2018). "Participant DC-C screened positive for hyperprolactinemia by exceeding our normal prolactin concentration range by only a fraction of a percentile, clearly an insufficient basis for a clinical diagnosis of hyperprolactinemia." (PMID 29515515, 2018). "At first, there are complaints related to hyperprolactinemia, such as galactorrhea, hypogonadism and infertility, leading to serum PRL measurement." (PMID 29768629, 2018). "Among 80 patients treated with fluoxetine, only 10 (12.5% developed hyperprolactinemia, with 38 ng/mL being the highest PRL level." (PMID 29768629, 2018).
hyperprolactinemia (continued). "In contrast, most patients with stalk dysfunction, drug-induced hyperprolactinemia or systemic diseases present with PRL levels < 100 ng/mL." (PMID 29768629, 2018). "Hyperprolactinemia is defined by prolactin levels above 15-18.77 ng/ml for males and 23-24.20 ng/ml in females." (PMID 34079927, 2018). "Other reasons included headache, hyperprolactinemia/prolactin co-expression, tumor near optic chiasm and cost." (PMID 29371335, 2018). "The dysregulation of PRL signaling contributes to tumorigenesis—including PRL-secreting adenomas or prolactinomas—leading to pathological hyperprolactinemia." (PMID 29622766, 2018). "This review will provide an overview of prolactin physiology, the role of stress in prolactin secretion, as well as the general clinical approach to hyperprolactinemia." (PMID 30627169, 2018). "Normal serum prolactin levels are <25 ng/ml in women and <20 ng/ml in men; hyperprolactinemia is defined as fasting serum levels above the normal values." (PMID 29805808, 2018). "In contrast, most patients with stalk dysfunction (pseudoprolactinomas), drug-induced hyperprolactinemia or systemic diseases present with PRL levels < 100 ng/mL." (PMID 29768629, 2018). "It is sometimes clinically challenging to differentiate a prolactin-secreting tumor from disconnection hyperprolactinemia because some cases demonstrate high-serum prolactin levels." (PMID 30407358, 2018). "Another important safety concern reported in patients treated with antipsychotics is elevated serum prolactin levels (hyperprolactinemia)." (PMID 29805808, 2018). "Although PRL elevation is usually mild (25-100 ng/mL) in cases of drug-induced hyperprolactinemia, it is also highly variable." (PMID 29768629, 2018). "There is a plethora of evidence supporting prolactin's role in the adrenal gland's response to stress, including that hyperprolactinemia increases secretion of ACTH, induces adrenal hypertrophy, and increases storage of cholesterol esters." (PMID 30627169, 2018). "Further understanding the role of prolactin in modulating emotional stress is essential and can provide further insight into systemic conditions arising secondary to hyperprolactinemia." (PMID 30627169, 2018). "In most studies, PRL levels were lower in macroprolactinemic patients than in those with monomeric hyperprolactinemia, but there was a great overlap between groups." (PMID 29768629, 2018). "Prolactinomas, one of the pituitary adenoma that synthesize prolactin (PRL), account for up to 45% of all pituitary adenomas and are highly associated with symptoms according to hyperprolactinemia in clinical practice." (PMID 30410470, 2018). "The magnitude of prolactin (PRL) elevation can be useful in determining the etiology of hyperprolactinemia." (PMID 29768629, 2018). "Of note, pimozide has been reported to block STAT5 activation in cultured cells, but this potential direct effect on STAT5 was overridden in vivo by hyperprolactinemia-induced PRL signaling." (PMID 29778097, 2018). "The magnitude of PRL elevation can be useful in determining the etiology of hyperprolactinemia because the highest values are observed in patients with prolactinomas." (PMID 29768629, 2018). "Hyperprolactinemia is a common finding in primary hypothyroidism, but increased prolactin in the setting of subclinical hypothyroidism (SCH) has been scarcely reported in the literature." (PMID 30079289, 2018). "Antidepressants induce hyperprolactinemia in a small proportion of patients, but they rarely elevate PRL to a significant degree." (PMID 29768629, 2018). "A misdiagnosis of hyperprolactinaemia can be due to the presence of macroprolactin or “big‐big” prolactin." (PMID 28980739, 2017). "According to the prolactinoma guidelines of the Endocrine Society, the diagnosis was based on clinical signs of hyperprolactinaemia, elevated levels of prolactin and a pituitary tumour on MRI." (PMID 27525431, 2017).
hyperprolactinemia (continued). "Although experimental studies showed that PRL has both beneficial and adverse effects on type 2 diabetes mellitus, clinical findings in subjects with hyperprolactinemia indicate adverse effects on glucose metabolism." (PMID 28384295, 2017). "A female hemodialysis patient with galactorrhea due to hyperprolactinemia was treated with different dialysis modalities to assess the effect on prolactin levels." (PMID 28791188, 2017). "It is important to note that these studies have been conducted during periods of chronic hyperprolactinemia, i.e., either during lactation or when PRL levels are experimentally elevated for a prolonged period of time." (PMID 28654010, 2017). "Hyperprolactinemia refers to a kind of pathologic status, in which the level of peripheral serum PRL increases continuously." (PMID 29317896, 2017). "Similar reductions in prolactin levels were seen following adjunctive use of APZ in haloperidol (HPD) treated patients with hyperprolactinemia." (PMID 29209406, 2017). "Hyperprolactinaemia should be excluded by checking prolactin concentration in all men with diminished sexual desire." (PMID 28980739, 2017). "Reduced prolactin clearance as well as reduced sensitivity to the inhibitory actions of dopamine and its agonists on prolactin release also contribute to hyperprolactinemia." (PMID 28529200, 2017). "Several clinical studies had reported a possible role of PRL in bone development during pregnancy, lactation, or hyperprolactinemia." (PMID 28152004, 2017). "It has previously been shown that prolactin treatment in guinea pigs results in hyperprolactinemia, producing bone dysmorphology of the otic capsule and hearing loss." (PMID 29354051, 2017). "This is because of the wide range (35–600 ng/ml) of hyperprolactinemia values occurring in pregnancy and the unclear correlation between circulating prolactin and pre-eclampsia." (PMID 28588552, 2017). "Average prolactin concentrations were three times higher in African than Asian elephants, due to the high percentage (28%) of Africans with consistently High prolactin indicating hyperprolactinemia (P < 0.05)." (PMID 27416141, 2016). "In such cases of drug-induced hyperprolactinaemia, prolactin elevation is usually mild but can be highly variable." (PMID 27716353, 2016). "in their retrospective study assessed the role of estrogen in women with a history of hyperprolactinemia and found that in a group of untreated patients, PRL levels decreased spontaneously during menopause." (PMID 26909481, 2016). "Prolactin immunoreactivity is by far the commonest in DG adenomas and, in fact, about 50 % of acromegaly patients present with signs and symptoms of hyperprolactinemia." (PMID 27245663, 2016). "The current Clinical Practice Guideline from the Endocrine Society for the diagnosis of hyperprolactinaemia recommends a single measurement of serum prolactin, with diagnosis confirmed by a level above the upper limit of normal." (PMID 27716353, 2016). "Patients with macroprolactinaemia generally do not require treatment, but the diagnosis is complicated by the fact that prolactin levels are highly variable and overlap with those found in patients with monomeric hyperprolactinaemia." (PMID 27716353, 2016). "Many patients with hyperprolactinaemia have a predominance of high-molecular-weight prolactin (macroprolactinaemia)." (PMID 27716353, 2016). "Prolactin, after polyethylene glycol precipitation was higher in patients with hyperprolactinemia than in women with macroprolactinemia and women with normal total prolactin concentrations." (PMID 26902871, 2016). "In this retrospective study with a long follow-up of patients with a history of hyperprolactinemia whose treatment with DA was stopped when they reached menopause, PRL levels normalized or decreased probably due to the fact that estrogen levels diminished." (PMID 26909481, 2016).
hyperprolactinemia (continued). "Sexual desire, sexual arousal, lubrication, orgasm, sexual satisfaction, and dyspareunia in subjects with monomeric hyperprolactinemia correlated with circulating levels of pre- and post-polyethylene glycol precipitation prolactin." (PMID 26902871, 2016). "Our findings that hyperprolactinaemia is associated with reduced BMD in schizophrenia provides additional support and impetus for the inclusion of regular PRL monitoring in guidelines for physical health monitoring in those with schizophrenia." (PMID 27696144, 2016). "Men with hyperprolactinemia, induced by prolactin-secreting tumors, were characterized by a higher prevalence of hypoactive sexual desire than matched healthy men." (PMID 26902871, 2016). "Multi-variable assessment of hyperprolactinemia (≥18 ng/ml prolactin) in African female elephants using repeated measures logistic regression." (PMID 27416141, 2016). "The results we present here also strongly suggest a role of AR is to repress prolactin secretion in males, and that ablating AR from the pituitary removes this repression resulting in a novel model of hyperprolactinaemia." (PMID 25799562, 2015). "Endocrinological evaluation showed a normal thyroid and adrenocortical function and a mild hyperprolactinemia (prolactin [PRL] 16.39 ng/mL, normal: 2.64–13.13)." (PMID 26181544, 2015). "Within this context, prolactin function promotes adaptive changes in a variety of body systems, but such actions can also be maladaptive, in a different context, if hyperprolactinemia occurs at an inappropriate time." (PMID 26101377, 2015). "In the long run, it deserves recommendation to remain cautious of sequelae of hyperprolactinemia such as hypogonadism and BMD loss, and to assess side-effects of prolactin-raising AP in each individual patient." (PMID 26309037, 2015). "A normalization of prolactin levels was noticed after surgery in all patients with hyperprolactinemia, mostly related to the complete relief of the pituitary stalk." (PMID 26474185, 2015). "The present study shows that adjunctive aripiprazole treatment in schizophrenia patients with risperidone-induced hyperprolactinemia results in a significant reduction in plasma concentrations of prolactin." (PMID 26448615, 2015). "Most disturbances of prolactin levels post TBI will manifest as hyperprolactinemia, due to inhibition of transport of prolactin inhibitory factor down the pituitary stalk into the gland." (PMID 26239686, 2015). "They suggested that the reduction in the inhibitory effect of dopamine in the hypothalamus can be a reason for inappropriate increased levels of LH and prolactin in PCOS patients with hyperprolactinemia." (PMID 25999998, 2015). "At the end of second month, 2 patients in treatment group had increased serum levels of prolactin (5.3%, 2/38), while, in control group, 17 patients experienced hyperprolactinemia (44.7%, 17/38)." (PMID 25973434, 2015). "Similar to our patient, this patient had erectile dysfunction and hyperprolactinemia despite normal levels of testosterone, suggesting that prolactin has different ways of exerting its effect on erectile function." (PMID 25844161, 2015). "The common side effect of antipsychotic treatments is the increase of prolactin (PRL) level (hyperprolactinaemia) that has received a little attention." (PMID 26239213, 2015). "In a placebo-controlled trial carried out in the Republic of Korea, concomitant aripiprazole treatment normalized prolactin levels in 88.5% of patients with haloperidol-induced hyperprolactinemia." (PMID 26448615, 2015). "This study was designed to evaluate the effect of cabergoline on menstrual irregularity and the level of serum androgens (testosterone, DHEAS and prolactin) in PCOS women with mild hyperprolactinemia." (PMID 25999998, 2015). "Chronic alcohol consumption increases PRL levels in blood and cell proliferation in pituitary PRL-producing cells known as lactotropes, resulting in hyperprolactinemia in human and animals." (PMID 26509893, 2015).
hyperprolactinemia (continued). "Mild to moderate hyperprolactinaemia reported in the three patients (27.3%) in this series was most probably secondary to pituitary stalk involvement compromising dopamine inhibition of prolactin production." (PMID 25045522, 2014). "To assess the involvement of serum PRL in the susceptibility of the mammary gland to carcinogenesis, we used OFA hr/hr rats and we compared the effects of parity and lactation or induced hyperprolactinemia on mammary carcinogenesis." (PMID 25136563, 2014). "We found that acute hyperprolactinemia, induced either by PRL administration or by dopamine receptor antagonism, reduced cell proliferation and increased apoptosis, indicating that these effects of PRL are dopamine-independent." (PMID 24859278, 2014). "In this paper, the author highlights the important findings pertaining to prolactin and schizophrenia, excluding the literature on drug-induced hyperprolactinemia which has been extensively reviewed elsewhere." (PMID 24800074, 2014). "The reasons for hyperprolactinemia are pressure on the pituitary stalk or simultaneous secretion of prolactin from tumor cells." (PMID 25511633, 2014). "In hyperprolactinaemia, amenorrhoea occurs due to inhibition of pulsatile GnRH secretion by increased prolactin levels." (PMID 25518745, 2014). "Pituitary adenoma is one of the most frequent causes of hyperprolactinemia, and prolactinoma accounts for a high proportion of hyperprolactinemia due to prolactin overproduction and oversecretion." (PMID 25142896, 2014). "Although Cushing's disease with hyperprolactinemia due to mixed ACTH- and PRL-secreting adenomas occurs rarely, elevated preoperative PRL levels in Cushing's disease are of diagnostic significance." (PMID 25506361, 2014). "As dopamine is the main prolactin inhibiting factor, hyperprolactinaemia is a common consequence of D2 receptor blockade in the tuberoinfundibular dopaminergic pathway by antipsychotic drugs." (PMID 24586772, 2014). "Pituitary stalk lesions, which can interrupt normal dopaminergic inhibition of PRL, often result in hyperprolactinemia." (PMID 23341953, 2013). "Comparison of prolactin levels and the frequency of subjects with hyperprolactinemia among each SSRI group." (PMID 24312671, 2013). "In a study by Abech and colleagues, 45.6% of cases presented positive IH to PRL and 30.6% of cases presented hyperprolactinemia." (PMID 23317095, 2013). "Amisulpride increases prolactin levels even in low doses, which means that decreased dose of amisulpride has little result on enhancing hyperprolactinaemia." (PMID 24490071, 2013). "The importance of prolactin has been further illustrated in the prolactin receptor mouse knockout, which has marked hyperprolactinaemia and a decrease in bone formation rate and reduced bone mineral density, as measured by DXA." (PMID 23690768, 2013). "The mean PRL levels were 51.36 and 10.84 ng/ml among those with hyperprolactinemia and normal PRL levels, respectively." (PMID 24312671, 2013). "PEG precipitation test revealed that hyperprolactinemia was almost exclusive due to the presence of the high-molecular prolactin isoform (MPRL = 10 107 mIU/L; recovery = 4,7%)." (PMID 23401806, 2013). "As plasma prolactin levels of the patient were elevated at the time of hospital admission, it seems that amisulpride related hyperprolactinemia was the most probable factor contributing to PE in this patient." (PMID 23533901, 2013). "With the advent of prolactin sparing antipsychotics, ample consideration needs to be given to the physiological consequences of hyperprolactinaemia in schizophrenic patients." (PMID 23690768, 2013). "Leães and colleagues identified hyperprolactinemia in 30.5%, presence of intracellular PRL in 21.9% and PRL-R in 39% of 82 cases, with positive correlation of serum PRL with presence of intracellular PRL." (PMID 23317095, 2013).